FUT4 (fucosyltransferase 4)
Diseases named in the same sentence as FUT4 in open-access papers (continued):
Sharing a sentence is not in itself a finding about the gene and the disease.
melanoma (continued). "To investigate the mechanism of Rg3 inhibition on melanoma tumor growth, we analyzed FUT4 expression in Rg3, FUT4 siRNA or combination treatment group by western blotting and immunohistochemical staining." (PMID 25672851, 2015). "We suggest that Rg3 deactivation of the EGFR/MAPK pathway through downregulating FUT4/LeY expression performs a key role in the treatment of melanoma." (PMID 25672851, 2015). "Our previous study showed that Rg3-induced EGFR/MAPK pathway deactivation inhibiting melanoma cells proliferation via decreasing FUT4/LeY expression." (PMID 26094873, 2015). "In our study, we found that Rg3 inhibited melanoma cell proliferation through downregulation of FUT4 both in vitro and in vivo." (PMID 25672851, 2015). "In conclusion, our results suggest that Rg3 deactivates NF-κB signaling pathway to downregulate FUT4 playing an important role in inhibiting melanoma progression." (PMID 26094873, 2015). "We discovered that Rg3 inhibited melanoma growth and induced apoptosis through inhibiting NF-κB/FUT4 signaling pathway and activating the extrinsic and the intrinsic apoptotic pathways both in vitro and in vivo." (PMID 26094873, 2015). "In the present study, we found that NF-κB/p65 dependent transcriptional regulation of FUT4 inhibited cell proliferation and induced apoptosis in human melanoma cells." (PMID 26094873, 2015). "In conclusion, Rg3 effectively inhibited melanoma cell growth by downregulating FUT4 both in vitro and in vivo." (PMID 25672851, 2015). "In the present study, we found that Rg3 significantly inhibited melanoma cell growth through inhibiting EGFR phosphorylation with FUT4/LeY low expression in vitro and in vivo." (PMID 25672851, 2015). "In the present study, we demonstrated, both in vitro and in vivo, that Rg3 suppressed FUT4 expression by inhibiting NF-κB signaling pathway, by which it induced melanoma apoptosis." (PMID 26094873, 2015). "Consistently, the inhibitory effect of the Rg3 and FUT4 knockdown on melanoma growth was also seen in a xenograft melanoma mouse model." (PMID 25672851, 2015). "To delineate the key FUT4-fucosylated target(s) mediating pro-invasive signaling in AR+ melanoma cells, we performed comparative proteomic profiling of fucosylated proteins purified from WM793 cells that ectopically expressed FUT4 vs. those that were knocked down for FUT4." (PMID 38326303, 2024). "We identified fucosyltransferase 4 (FUT4) as a key transcriptional target of AR that plays a crucial role in mediating androgen-stimulated invasiveness by disrupting cell-cell adhesion complexes in melanoma." (PMID 38326303, 2024). "Ectopic FUT4 expression reduced the number of N-cadherin:β-catenin and N-cadherin:δ1-catenin interactions per melanoma cell, whereas the depletion of FUT4 or treatment with 2F-peracetyl-fucose (2FF), a pharmacological inhibitor of FUTs39, enhanced these junction complexes." (PMID 38326303, 2024). "Therefore, our study delineates for the first time the pathological transcriptional regulation of FUT4 by AR and their downstream effectors and functional contributions to the metastatic spread of human cancer (melanoma)." (PMID 38326303, 2024). "Moreover, ectopic FUT4 expression rescued ARi-suppressed invasive capacity of melanoma cells back to baseline levels, whereas depletion of FUT4 abolished DHT-induced cell migration and invasion." (PMID 38326303, 2024). "Moreover, GSEA using the TCGA_SKCM cohort revealed that FUT4 expression is significantly associated with epithelial-mesenchymal transition (EMT) (p = 0.006; FDR = 0.018; NES = 1.9) and melanoma metastasis (p = 0.018; FDR = 0.018; NES = 1.7) signatures." (PMID 38326303, 2024). "Notably, androgen stimulation and FUT4 overexpression in melanoma cells also augmented their matrix (gelatin) degradative capacity." (PMID 38326303, 2024). "Other studies pointed toward a role of FUT4 in regulating melanoma cell growth." (PMID 34440905, 2021).
melanoma (continued). "Interestingly, administration of the ginsenoside Rg3, an herbal medicine with anti-tumor activity, suppresses the growth of human melanoma xenografts by decreasing the expression levels of FUT4 and p65 in vivo." (PMID 34440905, 2021). "Altogether, these studies suggest that suppression of FUT4 expression/activation by Rg3 may be a potential therapeutic strategy for melanoma treatment." (PMID 34440905, 2021). "Moreover, Rg3 combined with FUT4 siRNA showed stronger effect than the treatment with Rg3 or FUT4 siRNA alone in melanoma xenograft models." (PMID 25672851, 2015). "Rg3 is a potential FUT4 inhibitor and Rg3 combined with FUT4 siRNA may be a new therapy strategy in the treatment of melanoma." (PMID 25672851, 2015). "Together, these data indicate that AR-driven FUT4 signaling alters cell:cell adhesion by disrupting N-cadherin:catenin-containing junctional complexes between melanoma cells, supporting the notion that androgen/AR-FUT4 signaling promotes melanoma motility by altering cellular adhesion complexes." (PMID 38326303, 2024). "However, the antitumor effect of Rg3 on melanoma and its mechanism on FUT4 and LeY expression remains unknown." (PMID 25672851, 2015). "However, whether FUT4 is increased in melanomas, and whether FUT4 and NF-κB signaling pathway is involved in 20 (R)-Ginsenoside Rg3-induced melanoma cell apoptosis are largely unknown." (PMID 26094873, 2015). "Moreover, NF-κB signaling pathway blockage and FUT4 downregulation could be an effective approach in sensitization of the antitumor efficacy of Rg3 in human melanoma cells." (PMID 26094873, 2015). "Here the authors show that androgen-activated AR transcriptionally upregulates fucosyltransferase 4, which fucosylates L1CAM and promotes melanoma invasiveness by disrupting adherens junctions." (PMID 38326303, 2024). "Here, we delineate a previously undisclosed mechanism by which androgen-activated AR transcriptionally upregulates fucosyltransferase 4 (FUT4) expression, which drives melanoma invasiveness by interfering with adherens junctions (AJs)." (PMID 38326303, 2024). "In melanoma cells, steroid hormone-depleted CSS medium reduced FUT4 mRNA levels, which were restored ~3-4-fold either by steroid hormone-replete medium (10% fetal bovine serum (FBS)) or by supplementation with DHT alone." (PMID 38326303, 2024). "Of the 4 genes, androgen stimulation resulted in significant downregulation of FUK and upregulation of FUT4—suggesting that AR regulates FUK and FUT4 expression in melanoma cells (left)." (PMID 38326303, 2024). "Another report showed that Rg3 inhibits melanoma cell growth through inhibition of EGFR phosphorylation and FUT4/LeY downregulation in vitro and in vivo." (PMID 34440905, 2021). "However, the antitumor mechanism of Rg3, FUT4 and NF-κB pathway on human melanoma remains unclear." (PMID 26094873, 2015). "Targeting FUT4/LeY mediated fucosylation by Rg3 inhibited the activation of EGFR/MAPK pathway and prevented melanoma growth." (PMID 25672851, 2015). "We found that Rg3, FUT4 siRNA and Rg3 combined with FUT4 siRNA led to reduced activation of EGFR and ERK1/2 in A375 melanoma cells." (PMID 25672851, 2015). "Similar to CSS, treatment of WM793 or WM1366 melanoma cells with ARi suppressed their viability and proliferation—an effect that was not rescued by the ectopic expression of FUT4." (PMID 38326303, 2024). "FUT8-knockdown alone significantly reduced melanoma cell migration, an effect that was only partially rescued by the simultaneous overexpression of FUT4, suggesting that while both FUTs impact melanoma motility, their functional contributions are not redundant." (PMID 38326303, 2024). "Together, these observations functionally verify our phosphoproteomic analyses highlighting the enrichment of cell division-related pathways as AR-dependent, FUT4-independent as opposed to the enrichment of cell adhesion-/motility-related pathways as AR-/FUT4-dependent signaling in melanoma cells." (PMID 38326303, 2024).
melanoma (continued). "Notably, only FUT4 is highly expressed in melanoma, and its expression does not appear to correlate with that of other FUTs." (PMID 38326303, 2024). "One of the first pieces of evidence that fucosyltransferases might be implicated in melanoma progression came from the finding that the expression levels of FUT1 and FUT4 mRNA are significantly higher in metastatic melanoma cell lines (A375, WM9, WM239) compared to primary melanoma cells (WM35)." (PMID 34440905, 2021). "However, the mechanism of Rg3 on melanoma cell proliferation, and its potential role in regulation of FUT4 and LeY expression on cell proliferation have not been reported." (PMID 25672851, 2015). "Moreover, in a xenograft mouse model, Rg3 downregulated FUT4 and NF-κB/p65 expression and suppressed melanoma cell growth and induced apoptosis without any noticeable toxicity." (PMID 26094873, 2015). "Whereas manipulation of either or both FUT4 and L1CAM did not impact melanoma viability regardless of ARi treatment, the depletion of L1CAM abrogated DHT or FUT4-induced melanoma motility." (PMID 38326303, 2024).
brain tumor (17 papers, 2011 to 2025). "CD15 (FUT4, SSEA-1) has shown a particular interest as a cancer stem cells marker for pediatric brain tumors as HGGs and LGGs or MBs." (PMID 34277411, 2021).
colon carcinoma (17 papers, 2009 to 2025). "It has been reported that the overexpression of miR-200c inhibits the proliferation of colon cancer by targeting the FUT4/Wnt/β-catenin pathway." (PMID 36248422, 2022). "CD15/FUT4-high expressing colon cancer cells with primary resistance to cetuximab or bevacizumab are significantly more sensitive to MEK inhibitors than CD15/FUT4-low counterparts." (PMID 26427914, 2015). "FUT4/Lewisx overexpression is induced by the RAF-MEK-ERK signaling pathway, and colon cancer cells that are FUT4+Lewisx+ seem to exhibit significant resistance to the anti-EGFR (cetuximab) and the anti-VEGF (bevacizumab) chemotherapeutical agents." (PMID 29527514, 2018).
Sepsis (16 papers, 2016 to 2025). Sepsis is defined as life-threatening organ dysfunction caused by a dysregulated host response to infection. "Fucosyltransferase 4 (FUT4), a marker for premature/immature neutrophils that showed elevated expression in severe SARS-CoV-2 infection and is likely associated with poor outcomes in sepsis." (PMID 36143338, 2022).
bladder cancer (15 papers, 2017 to 2025). "FUT4 is overexpressed in multiple bladder cancer cell lines, promoting neoplastic cell proliferation and invasion." (PMID 40252176, 2025). "The anticancer effect of miR-125a-5p can be achieved by targeting FUT4, which acts as a tumor driver for bladder cancer progression." (PMID 38914670, 2024). "Studies have shown that miR-125a-5p can promote the growth and invasion of gastric cancer by regulating the hippo pathway, and miR-125a-5p can inhibit the progression of bladder cancer by targeting FUT4." (PMID 38914670, 2024). "As a functional microRNA, miR-125a-5p regulates the progression of bladder cancer by effecting on FUT4." (PMID 34195280, 2021). "MiR-125a-5p can inhibits cell proliferation and induce apoptosis, and reverse the EMT process of bladder cancer cells by targeting fut4, thereby, inhibiting tumor cell metastasis." (PMID 32596162, 2020). "Ultimately, strategies involving ST3GAL5 and ST8SIA1 overexpression, or inhibition of ST3GAL6, FUT4 and FUT7, could offer new therapeutic avenues for bladder cancer." (PMID 40252176, 2025).
gastric cancer (14 papers, 2012 to 2025). A primary or metastatic malignant neoplasm involving the stomach. "In gastric cancer, MYOD1 expression was significantly decreased, and suppresses the migration and invasion of gastric cancer cells by inhibiting FUT4 transcription." (PMID 36118887, 2022). "Gastric cancer cells treated with H. pylori CagA inhibited apoptosis through stimulating FUT4 fucosylation, which activated HSF1 transcription." (PMID 34064083, 2021). "Ginsenoside Rg3, the major compound in ginseng, was found to induce apoptosis through FUT4 inhibition via SP1 and HSF1 transcription regulation in gastric cancer cells with H. pylori CagA." (PMID 34064083, 2021). "In gastric cancer, the expression levels of ST3GAL3 and FUT4 mRNA were significantly enhanced in carcinoma tissues." (PMID 25923697, 2015).
leukemia (14 papers, 2012 to 2024). A malignant (clonal) hematologic disorder, involving hematopoietic stem cells and characterized by the presence of primitive or atypical myeloid or lymphoid cells in the bone marrow and the blood. "For example, it was shown that the miR-29b/Sp1/FUT4 axis promotes the malignant behavior of leukemia stem cells by regulating CD44 through the Wnt/β-catenin pathway." (PMID 39056681, 2024). "Among hematological cancers, FUT4 has been shown to increase malignancy of leukemia stem cells due to miR-29b, which inhibits the transcription factor Sp1 binding to FUT4 promoter." (PMID 36555445, 2022). "To date, few studies have examined the relationship between the FUT4 gene and leukemia, and most of these studies focused on myeloid leukemia cell lines." (PMID 32347296, 2020). "By increasing glycosylation, FUT4 can activate α5β1-mediated sequential signal transduction and accelerate adhesion and invasion between integrin α5β1 in leukemia cells and fibronectin in the extracellular matrix." (PMID 31831855, 2020). "The microRNA—miR-150, miR-34a, and miR-29b—have also shown significant anti-leukaemia effects by targeting wnt-signalling, mTOR signalling pathways, MYC, and Sp1/FUT4-fucosylations." (PMID 34207299, 2021).
hepatocellular carcinoma (13 papers, 2015 to 2024). A malignant tumor that arises from hepatocytes. "It has been described that fucosyltransferase 4 (Fut4), Fut6, and Fut8 are increased in hepatocellular carcinoma cells exhibiting a MDR phenotype dependant upon the PI3K/Akt pathway." (PMID 27446804, 2016). "The overexpression of fucosyltransferase 4 (FUT4), FUT6, or FUT8 is responsible for MDR in human hepatocellular carcinoma via activation of the PI3K/Akt signaling pathway, which induces P-gp expression." (PMID 36813234, 2023).
lung adenocarcinoma (13 papers, 2017 to 2025). A carcinoma that arises from the lung and is characterized by the presence of malignant glandular epithelial cells. "FUT4 is overexpressed in lung adenocarcinoma (LUAD) and is associated with the poor overall survival of LUAD patients, and a high expression of FUT4 promotes the metastasis of lung adenocarcinoma." (PMID 36552800, 2022). "FUT4 is a gene strictly involved in the PD1 axis, whose overexpression has been associated with a shorter survival in lung adenocarcinoma." (PMID 33014780, 2020). "Another Chinese team confirms that E-cadherin level does correlate with TAMs density, and reveals that TAMs promote a certain type of EMT in lung adenocarcinoma through FUT4/LeY-mediated fucosylation." (PMID 33262947, 2020). "We demonstrated that TAMs promote Ezrin phosphorylation-mediated EMT in lung adenocarcinoma through FUT4/LeY- mediated fucosylation." (PMID 28423676, 2017). "Together, our results revealed that TAMs promote Ezrin phosphorylation-mediated EMT in lung adenocarcinoma through FUT4/LeY- mediated fucosylation." (PMID 28423676, 2017). "In this study, we aim to analyze the role of FUT4/LeY-mediated fucosylation in TAMs-induced EMT in lung adenocarcinoma." (PMID 28423676, 2017). "TCM significantly promoted FUT4/LeY expression and Smad2/3 phosphorylation in lung adenocarcinoma cell lines (A549 and H1299) in a dose-dependent manner." (PMID 28423676, 2017). "FUT4 was reported to be involved in PD-1-related immunosuppression and could affect operable lung adenocarcinoma patient survival." (PMID 39040095, 2024). "On the basis of these findings, we concluded that M2 macrophages could promote FUT4/LeY expression in lung adenocarcinoma cells through the TGF-β1/Smad2/3 signaling pathway." (PMID 28423676, 2017). "Our results showed that M2 macrophages could significantly promote FUT4/LeY expression in lung adenocarcinoma cell lines." (PMID 28423676, 2017). "Thus, the blockade of the polarization of macrophages in tumors through targeting of FUT4/LeY is expected to provide new possibilities for immunotherapy in lung adenocarcinoma." (PMID 28423676, 2017). "Autophagic TAMs secrete TGF-β1 via the fucosyltransferase 4 (FUT4)/p-ezrin pathway, inducing EMT in lung adenocarcinoma cells." (PMID 39430253, 2024). "Moreover, M2 macrophages can promote the expression of FUT4/LeY through TGF-β1/Smad2/3 signaling, which mediates the development of EMT in lung adenocarcinoma by Ezrin phosphorylation." (PMID 33224886, 2020). "Importantly, FUT4/LeY is essential in cytoskeletal remodeling and EMT and the density of TAMs is intimately correlated with E-cadherin and LeY levels in lung adenocarcinoma." (PMID 33224886, 2020). "However, few studies have evaluated the N-fucosylation mediated by FUT4/LeY in lung adenocarcinoma; in addition, there is no report on the relationship between fucosylation and immune cells in the TME." (PMID 28423676, 2017).